GTSE1 (G2 and S-phase expressed 1)
Diseases named in the same sentence as GTSE1 in open-access papers (continued):
Sharing a sentence is not in itself a finding about the gene and the disease.
lung carcinoma (continued). "Furthermore, the proliferation, invasion, and migration of H460 and A549 lung cancer cells were promoted by ectopic expression of GTSE1 while being inhibited by knockdown of GTSE1." (PMID 34007784, 2021). "The upregulated GTSE1 was inseparable from the prognosis of lung cancer." (PMID 34007784, 2021). "Our data provide novel insight into targeting GTSE1 in radiosensitization of lung cancer." (PMID 32202046, 2020). "Furthermore, we detected the GTSE1 mRNA expression level in lung cancer tumor tissues." (PMID 34007784, 2021). "In summary, GTSE1 could play a crucial role in the development and progression of lung cancer." (PMID 34007784, 2021). "Therefore, the GTSE1 mRNA expression can act as a prognostic marker for patients with lung cancer." (PMID 34007784, 2021). "Thus, GTSE1 may serve as a therapeutic target and novel prognostic marker in lung cancer." (PMID 34007784, 2021). "Based on our results, we found potential and prospective clinical applications in GTSE1, NMU, FOS, and CDKN1C to act as prognostic markers in case of lung cancer." (PMID 32318583, 2020). "The demonstration of the potential medical value of GTSE1, NMU, FOS, and CDKN1C in the prognosis of patients suffering from lung cancer was done by us in order to verify the levels of expression of FOS, CDKN1C, NMU, and GTSE1." (PMID 32318583, 2020). "Analyzing the mRNA expression microarrays showed FOS, GTSE1, CDKN1C, and NMU are greatly harbored by the patients of lung cancer and are observed to be differentially expressed (fold change ≥2.0) of these genes." (PMID 32318583, 2020). "We strongly believe that GTSE1, NMU, FOS, and CDKN1C have potential and clinical application values to act as prognostic markers of lung cancer." (PMID 32318583, 2020). "So, we consider that GTSE1 may also facilitate tumor cell proliferation, migration, and invasion and suppress apoptosis via activating AKT signaling in lung cancer." (PMID 34007784, 2021). "However, the prognosis and roles of GTSE1 have not yet been investigated in the development of lung cancer." (PMID 34007784, 2021). "Additionally, CDKN1C, GTSE1, NMU, and FOS are not correlated with one another, which indicates that every target can individually be cast off as a predictive marker for lung cancer." (PMID 32318583, 2020).
hepatocellular carcinoma (11 papers, 2016 to 2024). A malignant tumor that arises from hepatocytes. "GTSE1 exerts a major effect on clone formation and has direct association with promoting proliferation in hepatocellular carcinoma (HCC) cells." (PMID 34007784, 2021). "High expression of GTSE1 has been reported to be associated with reduced sensitivity of hepatocellular carcinoma cells to 5-fluorouracil." (PMID 34876170, 2021). "Moreover, GTSE1 has been linked to the development of chemoresistance in osteosarcoma and hepatocellular carcinoma." (PMID 36092911, 2022). "Meanwhile, GTSE1 can also promote the malignant biological behavior of hepatocellular carcinoma by reducing the sensitivity of HCC cells to 5-FU." (PMID 36999057, 2023). "Upregulation of GTSE1 promoted cell proliferation and cell migration and invasion in the progress of hepatocellular carcinoma." (PMID 34007784, 2021). "Recent reports also claimed that this gene both at its mRNA and protein levels is extremely up-regulated in hepatocellular carcinoma specimens (silencing GTSE-1 expression inhibits proliferation and invasion of hepatocellular carcinoma cells)." (PMID 32318583, 2020). "Immunohistochemical methods revealed that cells with high expression levels of GTSE1 exhibited increased expression of N‐cadherin, β‐catenin, and Snail, indicating that GTSE1 might drive transformation of endothelial cells in hepatocellular carcinoma." (PMID 38715380, 2024). "Also, elevated GTSE1 significantly interferes with chemotherapy efficacy and influences the survival probability of patients with hepatocellular carcinoma (HCC)." (PMID 32082966, 2019). "Silencing GTSE-1 expression inhibits proliferation and invasion of hepatocellular carcinoma cells." (PMID 30564062, 2018). "GTSE1, also known as a regulated cytoskeletal protein, can promote cell migration and invasion in cervical cancer and hepatocellular carcinoma (HCC)." (PMID 36999057, 2023). "Previous research suggested GTSE1's functional role in hepatocellular carcinoma (HCC) proliferation, colony formation, invasion, and overall survival." (PMID 32082966, 2019). "By analyzing the hepatocellular carcinoma (HCC) datasets in GEO and TCGA databases, we showed that high expression of GTSE1 was correlated with advanced pathologic stage and poor prognosis of HCC patients." (PMID 32082966, 2019).
gastric cancer (10 papers, 2015 to 2024). A primary or metastatic malignant neoplasm involving the stomach. "GTSE1 methylation was found to be associated with better treatment response to DCX- chemotherapy in gastric cancer patients." (PMID 26209226, 2015). "In our study, loss of GTSE1 expression enhanced the anti-proliferative and growth-inhibitory effects of cisplatin in gastric cancer cells." (PMID 26209226, 2015). "Genes, such as ORC6 and GTSE1, are linked with drug resistance in various cancers, such as colon cancer and gastric cancer, but these genes may be liable for drug resistance in BRCA." (PMID 31311202, 2019). "In gastric cancer cells, GTSE1 expression inhibited apoptotic signaling and conferred resistance to cisplatin." (PMID 34007784, 2021). "GTSE1 expression represses apoptotic signaling and confers cisplatin resistance in gastric cancer cells." (PMID 32850327, 2020). "It has also been reported that the up-regulated expression of GTSE1 in gastric cancer cells has a contribution to cisplatin resistance." (PMID 30961661, 2019). "The present study demonstrated a major role of GTSE1 in conferring cisplatin resistance as knock down of GTSE1 expression in gastric cancer cells enhanced cisplatin sensitivity." (PMID 26209226, 2015). "Our findings suggest that GTSE1 mediates a caspase 3 independent cascade of apoptotic repression in cisplatin treated gastric cancer cells." (PMID 26209226, 2015). "This study also suggests the repressive role of GTSE1 in cisplatin induced apoptosis and signifies its potential utility as a therapeutic target for better clinical management of gastric cancer patients." (PMID 26209226, 2015). "Future studies should utilize animal models to further explore the therapeutic utility of GTSE1 in gastric cancer." (PMID 26209226, 2015). "GTSE1 expression in 4 gastric cancer cell lines- AZ521, SNU60, OCUM-1 and SNU719 was analysed by qPCR." (PMID 26209226, 2015). "This prompted us to further investigate the mechanism of cisplatin sensitivity in GTSE1 knocked-down gastric cancer cells." (PMID 26209226, 2015). "Since aberrant DNA methylation as a marker of platinum-resistance was shown in lung and ovarian cancer cell lines; we examined the methylation status of GTSE1 in gastric cancer patients who underwent neoadjuvant DCX-combinational chemo therapy." (PMID 26209226, 2015). "This study explored the expression, cellular localization and functional significance of GTSE1 in gastric cancer." (PMID 26209226, 2015). "The correlation between GTSE1 expression and methylation in gastric cancer cells was determined by RT-PCR and MSP respectively." (PMID 26209226, 2015). "A correlation between GTSE1 expression and cisplatin cytotoxicity is suggested here, as cisplatin treatment induced a dose dependent up regulation of GTSE1 in gastric cancer cells." (PMID 26209226, 2015). "The study presented here emphasizes the predictive value of GTSE1 as a biomarker for cisplatin resistance in gastric cancer." (PMID 26209226, 2015). "Nevertheless, our study identifies a previously uncharacterized role of GTSE1 in conferring cisplatin resistance and presents an additional avenue for future therapeutic intervention and patient stratification in gastric cancer." (PMID 26209226, 2015). "In this study, we aimed to identify the expression of GTSE1 and its correlation with cisplatin resistance in gastric cancer cells." (PMID 26209226, 2015).
gastric cancer (continued). "In order to verify the expression level of GTSE1 mRNA, we analyzed the public microarray database, Gene Expression Omnibus (Gastric cancer: a, GSE13911., b, GSE27242)." (PMID 26209226, 2015). "Here, we explored the contributory role of cell cycle dependent protein GTSE1 in gastric cancer chemoresistance." (PMID 26209226, 2015). "GTSE1 exhibited a differential methylation index in gastric cancer patients and in cell lines that correlated with DCX treatment response and cisplatin sensitivity, respectively." (PMID 26209226, 2015). "Taken together, our findings suggest a role of GTSE1 in enhancing the growth and survivability of gastric cancer cells where it acts antagonistic to the cellular sensitivity towards cisplatin." (PMID 26209226, 2015). "Interestingly, Cisplatin treatment induced a dose dependent up regulation as well as nuclear translocation of GTSE1 expression in gastric cancer cells." (PMID 26209226, 2015). "Taken together, by identifying the regulatory role of GTSE1 in cisplatin sensitivity and drug induced apoptosis, this study signifies the potential implications of GTSE1 as a biomarker for cisplatin resistance in gastric cancer." (PMID 26209226, 2015). "However, the current study was unable to show any significant survival benefit of GTSE1 methylation in gastric cancer patients." (PMID 26209226, 2015). "Moreover, cisplatin treatment induced a dose dependent upregulation as well as nuclear translocation of GTSE1 in gastric cancer cells." (PMID 26209226, 2015). "Consistently, GTSE1 was shown to be hypomethylated in gastric cancer cell lines." (PMID 26209226, 2015). "Of note, the decrease in cell proliferation and colony formation observed in GTSE1 knocked-down cells is also suggestive of its tumorogenic potential that could be utilized in targeted therapies in gastric cancer." (PMID 26209226, 2015). "Analysis of public gene array databases showed high GTSE1 expression in gastric cancer." (PMID 26209226, 2015). "Our study identifies GTSE1 as a biomarker for cisplatin resistance in gastric cancer cells." (PMID 26209226, 2015). "The study suggests GTSE-1 to play a major role in cisplatin resistance in gastric cancer cells." (PMID 26209226, 2015).
glioma (8 papers, 2021 to 2023). A benign or malignant brain and spinal cord tumor that arises from glial cells (astrocytes, oligodendrocytes, ependymal cells). "Taken together, the TAF15/LINC00665/MTF1(YY2)/GTSE1 axis has been acknowledged as an important axis in the modulation of the malignant features of glioma cells." (PMID 36429005, 2022). "The PABPC1-BDNF-AS-RAX2-DLG5 axis was shown to play the same role as the TAF15/LINC00665/MTF1(YY2)/GTSE1 axis in regulating the biological behavior of gliomas." (PMID 34178684, 2021). "Additionally, overexpression of TAF15 stabilizes LINC00665, leading to reduced STAU1-mediated mRNA degradation of both MTF1 and YY2, thereby restricting GTSE1 transcription and ultimately disrupting glioma’s malignant progression." (PMID 37403043, 2023). "Finally, MTF1 or YY2 silencing has reduced expression of GTSE1 oncogene in glioma." (PMID 36429005, 2022). "Additionally, the TAF15/LINC00665/MTF1(YY2)/GTSE1 axis is crucial for regulating the malignant biological behaviors of glioma cells, which might help in the development of a novel therapeutic strategy for human glioma." (PMID 34178684, 2021). "However, another view is that LINC00665 can act as a protective factor for glioma, inhibiting the malignant development of the tumor through the TAF15|LINC00665/MTF1|YY2/GTSE1 axis." (PMID 35563845, 2022). "In glioma, the TAF15|LINC00665/MTF1|YY2/GTSE1 axis inhibits malignant tumor progression.TATA-box-binding protein-associated factor 15 (TAF15) is a member of the FET family and plays an important role in regulating mRNA transcription, RNA splicing, and trafficking." (PMID 35563845, 2022). "LINC00665 promoted MTF1 degradation, and MTF1 bound to the promoter region of GTSE1 and transcription promoted GTSE1 expression, which proved that LINC00665/MTF1/GTSE1 axis played an important role in regulating the biological behavior of glioma cells." (PMID 36110851, 2022).
prostate carcinoma (7 papers, 2017 to 2024). A carcinoma that arises from epithelial cells of the prostate gland. "Up to now, numerous studies have demonstrated that GTSE1 is a potential risk gene for the development and progression of different tumors, including prostate cancer, BRCA, liver cancer, and others." (PMID 38715380, 2024). "SMC4 belongs to a family of genes linked with poor outcome in prostate cancer, and finally, GTSE1 was described as associated with worse prognosis in uterine leimyosarcoma." (PMID 28423514, 2017).
osteosarcoma (6 papers, 2021 to 2025). A usually aggressive malignant bone-forming mesenchymal neoplasm, predominantly affecting adolescents and young adults. "GTSE1 has been implicated in conferring cisplatin resistance in human osteosarcoma, though more studies are necessary to confirm its role in OSA tumorigenesis." (PMID 35456486, 2022). "Correlation analysis unveiled that GTSE1+ OB cells and monocytes were the negatively correlated populations at the single-cell level, a finding validated in 4 independent osteosarcoma datasets comprising 226 samples." (PMID 40831537, 2025). "Our findings suggest that GTSE1 overexpression serves as a potential biomarker for metastasis in osteosarcoma and provides a promising strategy to prevent metastasis by targeting GTSE1+ OB cells." (PMID 40831537, 2025). "This study aims to explore the effect of GTSE1 on the DNA damage repair and cisplatin (CDDP) resistance in osteosarcoma (OS)." (PMID 34876170, 2021).
liver cancer (5 papers, 2017 to 2024). An epithelial or non-epithelial malignant neoplasm that arises from the liver. "High expression of GTSE1 was associated with short overall survival of patients suffering breast cancer, bladder cancer, and/or liver cancer." (PMID 32082966, 2019). "Although previous researches have demonstrated the prognostic value of GTSE1 in various cancers, its underlying mechanisms in liver cancer remain to be characterized." (PMID 32082966, 2019). "Future studies validating the molecular mechanism underlying tumorigenesis and prognosis of liver cancer could emphasize the association between GTSE1 and minichromosome maintenance protein (MCM) family." (PMID 32082966, 2019). "However, the underlying mechanism of how GTSE1 interacts with other cell cycle-related genes to influence prognosis in liver cancer is still poorly understood." (PMID 32082966, 2019). "GTSE1 is well correlated with tumor progression; however, little is known regarding its role in liver cancer prognosis." (PMID 32082966, 2019). "In this study, we found that increased GTSE1 expression contributed to advanced pathologic stage and poor prognosis in liver cancer patients." (PMID 32082966, 2019). "The aim of the present study was to elucidate the role of GTSE1 in the prognosis of liver cancer and to find potential prognostic indicators in liver cancer." (PMID 32082966, 2019). "Among the DEGs, CDC20, PCNA, and MCM6 might synergistically affect regulations in cell cycle with GTSE1 and might be potential prognostic predictors in liver cancer." (PMID 32082966, 2019). "Upregulated GTSE1 expression in liver cancer was well correlated with a higher pathologic stage with significance (p = 0.0098), suggesting that GTSE1 might provide effective prognosis prediction." (PMID 32082966, 2019). "In this study, we integrated RNA microarray analysis with cellular experiments to identify the function of GTSE1 on liver cancer prognosis and found that three other cell cycle-related differentially expressed genes after GTSE1 knockdown could be applied in predicting prognosis of liver cancer." (PMID 32082966, 2019). "Thus, this study presents a key role for GTSE1 in the growth and progression of liver cancer." (PMID 28698581, 2017). "GTSE1, together with CDC20, PCNA, and MCM, presented unfavorable prognosis of liver cancer in our study." (PMID 32082966, 2019). "Genes like GTSE1, CDC20, PCNA, and MCM6 may be promising prognostic molecular biomarkers in liver cancer." (PMID 32082966, 2019).
lung adenocarcinoma (4 papers, 2020 to 2024). A carcinoma that arises from the lung and is characterized by the presence of malignant glandular epithelial cells. "Differential analysis was conducted to determine the expression level of GTSE1 in lung adenocarcinoma tissues." (PMID 39629227, 2024). "The aim of this investigation was to assess the diagnostic and therapeutic efficacy of G2 and S-phase expressed 1 (GTSE1) in lung adenocarcinoma (LUAD), while examining its impact on immune infiltration and drug treatment mechanisms." (PMID 39629227, 2024). "The mRNA levels of GTSE1 were elevated in squamous cell lung carcinoma and lung adenocarcinoma compared with normal lung tissues (fold change: 6.204 and 3.068, respectively)." (PMID 34007784, 2021). "This research was aimed to comprehensively investigate the expression levels, diagnostic and prognostic implications, and the relationship with immune infiltration of G2 and S phase‐expressed‐1 (GTSE1) across 33 tumor types, including lung adenocarcinoma (LUAD), through gene expression profiling." (PMID 38715380, 2024).
ovarian cancer (4 papers, 2015 to 2022). A primary or metastatic malignant neoplasm involving the ovary. "Particularly, we examined if ANPEP (from EC2), CASP14 and CLEC2B (from EC3), CADM3 and NRBP2 (from EC4), and SPC25, ESCO2, and GTSE1 (from EC5) are responsible for ovarian cancer cell proliferation by the cell viability assay." (PMID 34459128, 2021). "IHC staining data from 50 clinical samples in our hospital indicated that both of the expression scores of SLC31A1 and GTSE1 in ovarian malignant tumors were significantly higher than those in normal ovarian tissues (all p < 0.0001), they were positively correlated (R = 0.53, P < 0.001)." (PMID 36307842, 2022). "Additionally, our study identified a number of novel markers, such as CASP14, CLEC2B, CADM3, NRBP2, SPC25, ESCO2, and GTSE1, which are upregulated in a cluster‐specific manner and critical for ovarian cancer cell proliferation and migration." (PMID 34459128, 2021). "Eight genes (NUF2, GTSE1, DEPDC1, KIF18B, PBK, CEP55, HJURP, SKA1) were potential hub genes correlated to ovarian cancer progression." (PMID 35173547, 2022).